HOXD3 (homeobox D3)
Diseases named in the same sentence as HOXD3 in open-access papers (continued):
Sharing a sentence is not in itself a finding about the gene and the disease.
tumor (21 papers, 2009 to 2025). "This cluster was enriched in genes involved in differentiation and developmental processes (for example, SOX1 and SOX9, HOXD3 and HOXD8, and TBX4) and genes implicated as tumor suppressors (for example, SOX1 and SOX17, TSHZ3, WT1-AS, and FGF14)." (PMID 40931149, 2025). "In our previous, we found that expression of HOXD3 was extremely connected with tumor histology and tumor stage in LIHC." (PMID 37827698, 2023). "Overexpression of HOXD3 significantly reduced tumor volume tumor weight and size compared with LV-NC." (PMID 37827698, 2023). "Our first pan-cancer analyses of HOXD1, HOXD3, and HOXD4 indicate that those factors were differentially expressed between normal and tumor tissues and reveal associations of gene expression with clinical indicators." (PMID 37827698, 2023). "HOXD3 reversed the tumour proliferation–suppressing effect of YY1 on HMCC‐97H and Huh7 cell proliferation." (PMID 32557953, 2020). "Meanwhile, matrine restrained tumor growth of HCC by regulating circ_0027345/miR-345-5p/HOXD3 axis in vivo." (PMID 32549793, 2020). "The HOXD-AS1-overexpressing tumours also raised H3K27me3 protein level and reduced HOXD3 expression and Ki-67 index in xenografts by IHC." (PMID 30823921, 2019). "Studies proved that HOXD3 expression was a significant unfavorable prognostic factor for tumor patients." (PMID 30115812, 2018). "To further demonstrate that miR-203a suppressed tumor progression through targeting HOXD3, we constructed a HOXD3 overexpression vector and co-transfected it with miR-ctrl or miR-203a into SMMC-7721/Hep3B cells." (PMID 27244890, 2016). "Expression of HOXD3 in tumor tissues was assessed by qRT-PCR and western blotting." (PMID 37827698, 2023). "Furthermore, in the KIRC, all HOXD1, HOXD3, and HOXD4 expressions were negatively linked with the tumor stage." (PMID 37827698, 2023). "Consistent with the results in vitro, matrine could inhibit tumor growth in vivo by inducing miR-345-5p and reducing circ_0027345 and HOXD3." (PMID 32549793, 2020). "Our previous research confirmed that miR‐203a could target HOXD3 3′ UTR region via EGFR and VEGFR to suppress cell progression in SMMC‐7721 and Hep3B cells, suggesting that HOXD3 was important for tumour development." (PMID 32557953, 2020). "In our research, we found that YY1 could suppress tumour progression by directly targeted HOXD3 via ITGA2‐ERK cell signalling." (PMID 32557953, 2020). "In addition, that mice injected with HOXD3‐downexpressing cells formed smaller tumours compared with the controls." (PMID 32557953, 2020). "LAT and NFE2L3 were upregulated in tumor samples, while HOXD3 was downregulated." (PMID 31777602, 2019). "HOXD3 regulates cell adhesion processes and enhancing invasion and metastasis of tumor cells." (PMID 30115812, 2018). "The present study therefore suggests that miR-203a may act as a tumor suppressor and HOXD3 may play the role of an oncogene; and thus, may provide a beneficial strategy for future HCC therapy." (PMID 29402992, 2018). "However, the mechanism by which HOXD3 regulates the expression of oncogenes and tumor suppressors in tumor proliferation, invasion, metastasis, and angiogenesis has not been reported." (PMID 29402992, 2018). "Next, we silenced HOXD3 expression by RNAi to test whether HOXD3 is involved in the anti-tumor effects of miR-203a." (PMID 27244890, 2016). "Furthermore, expression levels of miR-203a and HOXD3 in tumor tissues were examined by qRT-PCR and western blot." (PMID 27244890, 2016). "However, little is known about the mechanisms by which HOXD3 affects tumor proliferation and apoptosis, especially in HCC." (PMID 27244890, 2016). "In addition, we found that HOXD3 overexpression counterbalanced the tumor suppressing effect of miR-203a on HCC cell proliferation." (PMID 27244890, 2016).
tumor (continued). "When analyzed as a dichotomized variable, HOXD3 methylation was found significantly associated with progression in univariate log-rank analysis as well as in multivariate analysis adjusting for age, Gleason score, pre-operative PSA, and pathological tumor stage." (PMID 25238417, 2014). "We specifically chose HOXD3 as it represents an interesting class of genes that appear to show a pattern of increased methylation correlating with tumour grade progression according to the classic Gleason pattern grading system within Gleason score 6 and 8 tumours." (PMID 19283074, 2009). "In our previous study, we demonstrated that HOXD3 was upregulated in HCC and promoted tumour metastasis by inducing the expression of EGFR and ITGA2 in HCC cells and tissues, indicating that HOXD3 is a crucial angiogenic factor in HCC." (PMID 38493218, 2024). "HOXD1, HOXD3, and HOXD4 are members of the HOXD genes family and are related to tumorigenesis of the tumor." (PMID 37827698, 2023). "In varying degrees, HOXD1, HOXD3, and HOXD4 participated in the initiation and progression of the tumor." (PMID 37827698, 2023). "The data in vivo proved that matrine hindered the tumor growth of HCC by up-regulating miR-345-5p and down-regulating circ_0027345 and HOXD3." (PMID 32549793, 2020). "The HOXD3 gene, which is a member of the HOX transcription factor gene family, has been shown to be expressed in several tumor cell lines that exhibit enhanced invasion and metastasis through the coordinated expression of metastasis-associated factors." (PMID 29402992, 2018). "We have previously discovered and/or characterized tumor-specific DNA methylation of six genes (APC, GSTP1, HOXD3, KLK10, TBX15, and TGFβ2) in radical prostatectomy tumor samples." (PMID 30470249, 2018). "In this context, our results demonstrate that overexpression of miR-203a inhibits HOXD3, which then indirectly leads to down-regulation of the VEGFR pathway, thereby suppressing tumor invasion, migration, and angiogenesis in HCC." (PMID 29402992, 2018). "Strikingly, high HOXD3 levels were significantly associated with poor tumor histology (well: 57.9% (11/19); moderate: 66.7% (6/9); poor: 90.0% (27/30) (P = 0.023), but not with age or gender, suggesting that upregulated HOXD3 protein expression might be involved in the progression of HCC." (PMID 27244890, 2016). "However, other genes, such as HOXB1, HOXC5, HOXC12, HOXD3, and HOXD12, have extremely low expression levels, suggesting that they are more expressed in normal tissue samples than in tumor samples." (PMID 39980564, 2025). "The results showed downregulation of HOXD3, PRUNE2, CD302, CCDC8, and KLF2 (tumor vs. control)." (PMID 41186818, 2025). "Therefore, HOXD3 can facilitate HCC metastasis by upregulating CCR6 expression, and CCR6 co-ordinates the tumour progression by playing the multiple functions on HCC and ECs." (PMID 38493218, 2024). "Therefore, In the KIRC, all of HOXD1, HOXD3, and HOXD4 expression was significantly correlated with tumor stage (shown in red square frame)." (PMID 37827698, 2023). "Furthermore, the expression of N-Cadherin, MMP2, CDK4, and cyclinD1 was significantly elevated, and E-cadherin was inhibited in ccRCC cells that knocked down HOXD3, suggesting a tumor-suppressive role for HOXD3 in KIRC tumor." (PMID 37827698, 2023). "Tumor Immune Estimation Resource, Single-Cell Analysis, and gene set enrichment analysis (GSEA) were performed to investigate the special functions and mechanisms of the HOXD1, HOXD3, and HOXD4 in cancers." (PMID 37827698, 2023). "While the involvement of HOXD3 in matrine-mediated anti-tumor processes in HCC has not been investigated." (PMID 32549793, 2020). "Sodium bisulfite sequencing (BSP) was used to validate the 6 randomly selected candidate islands, in which the results of 5 mapped genes (ANKRD45, CDX1, APC, HOXD3 and TUBB6) showed significant differences in the 10 pairs of validation tumor and adjacent tissue cohorts." (PMID 28418032, 2017).
tumor (continued). "Moreover, HOXD1, HOXD3, and HOXD4 could be applied to evaluate immune cells’ infiltration in various tumor tissues." (PMID 37827698, 2023). "Furthermore, the expression of HOXD3 and ITGA2 in LV‐shHOXD3 tumours was lower than that in control tumours, and the expression of HOXD3 and ITGA2 was notably decreased in the HOXD3‐downexpressing treated tumours as compared with that in the control treated tumours at protein levels." (PMID 32557953, 2020). "By methylation analysis of 232 RP specimens using qMSP, Kron and colleagues found that HOXD3 was a significant independent predictor of BCR in univariate log-rank analysis, but not in multivariate Cox regression analysis adjusting for Gleason score, tumor stage, and surgical margin status." (PMID 25238417, 2014).
cancer (17 papers, 2009 to 2024). A tumor composed of atypical neoplastic, often pleomorphic cells that invade other tissues. "HOXD3 was remarkably associated with the clinical stage of cancers, including ACC, ESCA, KICH, KIRC, KIRP, and THCA (p < 0.05)." (PMID 37827698, 2023). "Several of the genes, such as Mmp8, Dock10, Hoxd3 and Fat3, have previously been reported to show mutation or altered expression in cancer and particularly metastasis." (PMID 28577549, 2017). "HOXD3 is associated with progression of multiple types of cancer." (PMID 32557953, 2020). "GSEA was performed to assess the signaling pathways of HOXD1, HOXD3, and HOXD4 that cause their differential expression in each cancer." (PMID 37827698, 2023). "Above all, these results indicated that HOXD1, HOXD3, and HOXD4 expression was significantly enriched with pathways associated with the immune-activation status and progression of cancers." (PMID 37827698, 2023). "We studied the expression level of the ANKRD45 and HOXD3 genes in cancer tissue and adjacent tissue using quantitative PCR." (PMID 28418032, 2017). "In addition, HOXD3 was positively associated with the CAF, Endo, macrophages, dendritic, CD8+ T, and Tregs cells in most of the cancers and negatively correlated with the γ/δT cells in most cancers, especially in KIRC." (PMID 37827698, 2023). "This suggests that HOXD3 plays a different role in various cancers." (PMID 37827698, 2023). "However, the function of HOXD3 in cancer onset and upstream/downstream regulation maintenance requires further investigation; especially, the relationship between HOXD3 and YY1 in HCCs has rarely been studied." (PMID 32557953, 2020). "HOXD3 expression was higher in cancer tissue than in normal tissue." (PMID 27244890, 2016). "Specifically, statistically significant MPMR elevations, with fold changes of 2.01, 1.36, and 2.61, were identified on the promoters of HOXA9, the HOXD3 genes of cancer patients, and the RASSF1A promoter of non-cancer patients, respectively." (PMID 39123492, 2024). "Meantime, HOXD1, HOXD3, and HOXD4 co-inhibition was demonstrated in 7 cancers, such as BRCA, COAD, KICH, KIRC, KIRP, READ, TGCT." (PMID 37827698, 2023). "Results confirmed that differential expression of HOXD1, HOXD3, and HOXD4 between cancer tissues and normal tissues existed in many types of cancer." (PMID 37827698, 2023). "The current study conducted the bioinformatics database to analyze the expression of HOXD1, HOXD3, and HOXD4 in common cancers." (PMID 37827698, 2023). "Meantime, the GSEA result showed that HOXD1, HOXD3, and HOXD4 were connected with the immune infiltration in pan-cancer." (PMID 37827698, 2023). "HOXD3 is the third paralog of the HOXD family and has been shown to play a pivotal role in cancer cell invasion, metastasis, and angiogenesis." (PMID 30823921, 2019). "In urine DNA, some markers like HOXD3, HOXA7, GPR62 and KLK10 were detected with comparable frequency from all cancer patients and are candidates for biomarker panels used for the early detection of PCA." (PMID 31297302, 2019). "HOXD3, a member of the HOX transcription factor gene family, has been reported to be aberrantly expressed in some cancers." (PMID 30823921, 2019). "Furthermore, the expression of HOXD1, HOXD3, and HOXD4 remarkably correlated with histological grade was demonstrated in 11 cancer types." (PMID 37827698, 2023). "Our findings suggest that HOXD1, HOXD3, and HOXD4 expression will bring different prognostic outcomes, which needs to be further studied for the specific role of HOXD1, HOXD3, and HOXD4 in each cancer." (PMID 37827698, 2023). "Whereas, the molecular function of HOXD1, HOXD3, and HOXD4 in tumorigenesis, recurrence, and metastasis of various cancers have still unknown." (PMID 37827698, 2023). "Moreover, it suppressed the anti-apoptotic protein Survivin to inhibit HepG2 proliferation, and the transcription factor Homeobox D3 (HOXD3), hampering the metastatic process and angiogenesis of various cancer cells." (PMID 34069740, 2021).
HOXD3 also shares sentences with these, for which no sentence is quoted: lung adenocarcinoma (2 papers); melanoma (2); ovarian carcinoma (2); renal cell carcinoma (2); anencephaly (1); astrocytoma (1); brain tumors (1); diabetes (1); diabetic foot ulcerations (1); insulinoma (1); leukemia (1); Lung squamous cell carcinoma (1); oligodendroglioma (1); Pheochromocytoma and paraganglioma (1); Primary amenorrhea (1); Primary hypothyroidism (1); primary immunodeficiency (1); renal carcinoma (1); venous ulcers (1).